RNU4-78P (RNA, U4 small nuclear 78, pseudogene)
Gene: Small nuclear RNA gene on chromosome 3 (42,221,840 to 42,221,965, forward strand). Ensembl gene ENSG00000222872.
Homologues: Orthologues: chimpanzee U4 (98% identical), macaque U4 (87% identical). Paralogues in human: RNU4-7P (86% identical), RNU4-68P (84% identical), RNU4-13P (83% identical), RNU4-67P (83% identical), RNU4-76P (83% identical), RNU4-58P (83% identical), RNU4-9P (83% identical), RNU4-42P (82% identical), RNU4-23P (80% identical), RNU4-44P (80% identical), RNU4-92P (80% identical), RNU4-80P (79% identical), and 81 more.